LEP (leptin)
Diseases named in the same sentence as LEP in open-access papers (continued):
Sharing a sentence is not in itself a finding about the gene and the disease.
Obesity (continued). "Indeed, studies in consanguineous families led to the discovery of the first homozygous loss-of-function mutations in the genes encoding leptin (LEP;) and the leptin receptor (LEPR;) associated with severe obesity." (PMID 34748544, 2021). "Interestingly, mice exposed to lower doses of phytoestrogen during gestation and lactation present a lower birth weight, but develop obesity, high leptin, and 17β-estradiol (E2) levels, and impaired glucose metabolism." (PMID 34940512, 2021). "After a period of training, serum leptin decreases in obesity together with fat mass." (PMID 34047810, 2021). "In addition, obesity-induced elevated leptin levels promote a significant alteration of the gliovascular interface in the hypothalamus, causing arterial hypertension." (PMID 34827650, 2021). "Whilst several hypothalamic-acting, blood-borne hormones – including the active thyroid hormone (T3), oestrogen and glucagon-like peptide-1 (GLP-1) – have been reported to regulate obesity, here we will focus on the dysregulation of leptin signalling within the hypothalamus." (PMID 34613819, 2021). "Single nucleotidepolymorphism (SNP) in the leptin and leptin receptor(LEPR) have been studied as factors that may be associated with PCOS and obesity, which is reported in morethan half of the women with PCOS." (PMID 33687165, 2021). "In addition to altered levels of leptin and adiponectin, increased levels of obesity-related adipokines such as interleukin-6 (IL-6), interleukin-8 (IL-8), tumor necrosis factor-α (TNF-α), visfatin and resistin are associated with increased cancer risk." (PMID 33987528, 2021). "The immune dysregulations include increased levels of inflammatory markers such as C - reactive protein (CRP), interlukin-6 (IL-6), tumour necrosis factor alpha (TNF alpha), and other cytokines indicating insulin and leptin resistance, obesity, inflammation, and higher rates of metabolic syndrome." (PMID 34895175, 2021). "It is well known that leptin plays a key role in the pathogenesis of obesity-induced hypertension." (PMID 34276408, 2021). "The leptin resistance typically documented in obesity could thus contribute to the observed anomalies in lactogenesis." (PMID 33751362, 2021). "Another obesity gene leptin, a precursor of adipokinases, is also secreted by adipose tissue." (PMID 34784930, 2021). "Our study revealed that in children with overweight and obesity, leptin and fibrinogen concentrations are strongly correlated to the VO2max and may predict the latter." (PMID 33669882, 2021). "+/− mice have reduced diet-induced obesity and leptin resistance." (PMID 34502119, 2021). "It was suggested that exogenous sources of leptin could also be used in individuals with obesity, who were thought to lack sufficient leptin." (PMID 34899599, 2021). "The results verify that in children with obesity, VO2max may be predicted from hematological parameters (leptin and fibrinogen), possibly bypassing more invasive methods." (PMID 33669882, 2021). "Leptin resistance, in addition to impaired lipolysis, might contribute to the development of diet-induced obesity in adG6AKO mice." (PMID 33428938, 2021). "Elevated levels of pro-inflammatory adipokines such as leptin, visfatin and resistin, as found in obese individuals, may represent another crucial pathomechanistic link for how obesity might contribute to compromised periodontal healing." (PMID 34948136, 2021). "These incompatibilities may be explained, in part, by the presence of confounding factors—obesity and related conditions, such as leptin resistance and components of metabolic syndrome." (PMID 34679472, 2021). "Akin to leptin resistance in obesity, increased FGF21 and GDF15 levels in obesity might indicate resistance to these cytokines, and a concomitant decrease in function, though this remains unresolved." (PMID 34777390, 2021). "Transport of leptin into the CNS is saturable at higher levels of serum leptin in obesity." (PMID 33848268, 2021).
Obesity (continued). "Previous studies have revealed that in vitro 100 ng/ml leptin treatment, which indicates obesity in vivo, led to increased expression of IFN-γ, perforin, granzyme B, and CD69, together with increased direct cytotoxicity by human NK cell lines, including NK92 and YT cells." (PMID 33717101, 2021). "Thus, the appetite suppression and weight loss induced by celastrol or GA-02 indicate a crucial link between leptin signaling re-sensibilization and hypothalamic inflammation suppression, pointing to a likely possibility for obesity control." (PMID 34526895, 2021). "Coming back to the endocrine system, both insulin resistance and leptin resistance illustrate best how obesity status reprograms hormonal functions during obesity via modifying the interaction quality of energy balance-control hormones with their target tissues." (PMID 33450943, 2021). "Additionally, leptin action and IS partially mediate the relationship of obesity with excess energy intake." (PMID 34206460, 2021). "Furthermore, obesity-induced modulation in the adipokines leptin and adiponectin results in a net inhibition of AMPK." (PMID 33859943, 2021). "Moreover, in this young population, the interactions between either age and obesity or between age and gender, or the role of leptin on REE are not clearly understood." (PMID 33917063, 2021). "In addition, genetic deletion of Rap1 in the forebrain protects mice from HFD-induced metabolic disturbances, such as neural leptin resistance, obesity, and glucose imbalance." (PMID 33974562, 2021). "Chronic inflammation involves obesity and elevates insulin resistance, which gives rise to an abnormal production adipocytokines such as leptin, tumor necrosis factor α, prothrombotic mediator plasminogen activator inhibitor-1 (Pal-1), interleukin-1, and interleukin-6." (PMID 35223819, 2021). "Two central endocrine pathways in obesity are those of insulin and leptin." (PMID 34211985, 2021). "During the progression of obesity, leptin signaling is affected, leading to leptin resistance." (PMID 33557185, 2021). "Leptin (ob/ob) and leptin receptor (db/db) deficient mice are obesity models with spontaneous mutations resulting in lack of leptin signaling." (PMID 33937257, 2021). "Another important factor that could be contributing to the immune imbalance in COVID-19 patients with obesity is chronically higher adipokines, such as leptin." (PMID 34220807, 2021). "Therefore, in the present section, we briefly discuss potential outcomes for folliculogenesis associated with changes in the secretory profile of main adipokines other than leptin during obesity." (PMID 33924072, 2021). "In addition, particularly in adults with obesity, it can lead to a decrease leptin production, which in turn contributes to a reduction of adipose tissue accumulation." (PMID 32896055, 2021). "Under obesity conditions, the pharmacological capability of these compounds to achieve a “partial” reduction of bioactive leptin levels has shown crucial benefits, including an enhanced leptin sensitivity in the central nervous system and a higher degree of peripheral leptin sensitivity." (PMID 34899599, 2021). "Short sleep duration is believed to be related to higher levels of ghrelin hormone and decreased leptin hormone level, which could potentially lead to increased appetite, food intake, obesity, and impaired glucose tolerance." (PMID 33921201, 2021). "Obesity might also trigger thyroid autoimmunity by dysregulating the pituitary-hypothalamic axis and adipose tissue via leptin." (PMID 34122544, 2021). "Thus, some adipokines and acute phase proteins such as CRP, IL-6, TNF-α, and leptin, have been widely studied and are considered to be proinflammatory biomarkers of obesity and MetS progression in children and adolescents." (PMID 33498461, 2021). "Leptin resistance is a major pathophysiological factor of obesity." (PMID 34671315, 2021).
Obesity (continued). "The pathogenesis of diabetes is different from that of obesity, and reports have shown that it might be related to leptin hyposecretion or leptin resistance." (PMID 34446063, 2021). "Leptin is a signaling molecule derived from adipose tissue, and regulates energy metabolism by inhibiting food intake, generating energy expenditure, and restoring normo-glycemic levels, but leptin resistance limits these functions during obesity." (PMID 34037093, 2021). "The C57BL/6J model has been extensively investigated to study diet induced obesity and metabolic syndrome as it displays increased body weight/fat mass accumulation, leptin resistance and adipose distribution, closely mimicking the disease progression that occurs in humans." (PMID 34068953, 2021). "Thus, leptin is an interesting target for future mechanistic research on factors involved in obesity immune dysregulations affecting influenza and COVID-19 pathogenesis." (PMID 33816341, 2021). "Our results in patients with CLD are contrary to findings in children with idiopathic, hyperleptinemic obesity who typically have normal or high IGF1 that decreases with weight loss, and suggest that in patients with CLD leptin increases IGF1 levels and promotes linear growth." (PMID 34002033, 2021). "The central satiety effects of leptin are abrogated in obesity." (PMID 34722411, 2021). "Previous studies by our group with obese adolescents found that semi-intensive therapy was effective to improve body composition, HDL-cholesterol, leptin concentration and nutritional profile, suggesting that this kind of intervention can be used to treat obesity." (PMID 34762789, 2021). "Packer postulated that obesity aggravates the deleterious interaction of leptin with the renin–angiotensin–aldosterone system and the renal sympathetic system leading to overactivity of neprilysin and, thus, deficiency in endogenous natriuretic peptides in these patients." (PMID 33723360, 2021). "Since obesity is characterized by an increase in both leptin and FFAs, β-oxidation-induced mitochondrial ROS production may be enhanced even further with excess bodyweight." (PMID 33859943, 2021). "Leptin plays a key role in the regulation of both energy metabolism and obesity, and also takes part in different diseases and processes, including (but not limited to) reproduction, autoimmunity, glucose metabolism, non-alcoholic fatty liver disease or cancer." (PMID 34827640, 2021). "PTPN1 is a risk-factor gene linked to diabetes and obesity, which has a direct involvement in the insulin and leptin signaling pathways, and that mice lacking this gene were resistant to weight gain and intolerant to glucose." (PMID 34220925, 2021). "While it has been reported that OC patients who were suffering from obesity (higher LEP expression/serum levels) had worse overall survival and progression-free survival, other studies reported an inverse relationship between LEP levels and the survival rates of OC patients." (PMID 34884678, 2021). "Leptin, a hormone secreted by adipocytes, can regulate the systemic energy metabolism, while it is also involved in regulating immunity and promoting the progression of autoimmune diseases, obesity-related cardiovascular diseases." (PMID 34122419, 2021). "Although leptin at physiological levels may exert therapeutic effects, pathophysiological amounts of leptin, mimicking diabetes or obesity, exhibit potent proatherogenic properties." (PMID 34064112, 2021). "Similarly, levels of leptin, an adipokine, remain high during obesity as a consequence of leptin resistance." (PMID 35822048, 2021). "Leptin levels increase according to the severity of obesity in both groups." (PMID 35126755, 2021). "Leptin is an adipokine involved in regulating energy homeostasis and obesity." (PMID 33796069, 2021).
Obesity (continued). "Combined, these results demonstrate that obesity is associated with greater CD4+ T cell proliferation among PLWH, and that higher circulating leptin levels in obesity may contribute to improved CD4+ T reconstitution in PLWH initiating ART." (PMID 35111163, 2021). "By contrast, high leptin levels have also been associated with hepatic steatosis and NAFLD pathogenesis since a high percentage of NAFLD patients have been observed to suffer obesity, which is closely related with hyperleptinemia." (PMID 34209386, 2021). "In these models, obesity is caused by the lack of leptin (the ob/ob mouse), or by a mutation in the leptin receptor gene (db/db mouse), both causing the mice to overfeed." (PMID 33987528, 2021). "As overweight is the consequence of a positive energy balance and is accompanied by higher amounts of adipose tissue, it is not surprising to associate obesity with high circulating levels of leptin." (PMID 34064024, 2021). "Thus, manipulation of sphingolipid levels with drugs or nutrients can be useful approaches for the treatment of obesity by clinicians, particularly by aiming to decrease ceramide levels to have a positive effect on insulin/leptin resistance." (PMID 34069652, 2021). "This study may provide a basis for relevant studies on the acupuncture treatment of leptin resistance in obesity." (PMID 34260523, 2021). "The data may be explained by increased leptin levels (a pro‐inflammatory adipokine) observed in individuals with obesity." (PMID 34269511, 2021). "Genetic studies demonstrated that single nucleotide polymorphisms (SNPs) in the MC4R, LEP, and LEPR genes could be linked with obesity." (PMID 34205732, 2021). "Furthermore, serum leptin and resistin have specific roles in the regulation of adipose tissue macrophages in patients with modest obesity or early metabolic dysfunction." (PMID 34576066, 2021). "Importantly, obesity secondary to leptin resistance was found to result in increased salt sensitive blood pressure response to high salt in SHHF rat, a model of spontaneous hypertension." (PMID 34966295, 2021). "Besides the pleiotropic mechanisms by which obesity impairs immunity, the higher leptin concentrations which characterize obesity substantially contribute to such dysregulation of the immune response." (PMID 33804765, 2021). "While the current literature has many excellent reviews discussing the contribution of different adipokines in the etiology of obesity and related metabolic and cardiovascular disorders, the role of leptin in pathogenesis of atherosclerosis has been somewhat conflicting." (PMID 34064112, 2021). "The hypothesis under which this study was designed was that if the obesity paradox holds true, and leptin is an easily available marker for total body fat mass, its concentrations should be inversely related to the risk of DCI and unfavorable outcomes." (PMID 33866464, 2021). "Leptin is known to be safe for human use and it is already licensed as an anti-obesity treatment." (PMID 33440796, 2021). "Recently, a relationship between the olfactory system and the endocrine system, in terms of gherkin and leptin (peptides important in appetite control and obesity pathogenesis), has been demonstrated, as their receptors are expressed in the olfactory mucosa and regulated by starvation." (PMID 34577836, 2021). "Additionally, the peptide hormone, leptin, secreted primarily from adipose tissues and is a marker of obesity, is also secreted from cartilage tissue cells, including nucleus pulposus (NP) cells of intervertebral discs." (PMID 33776562, 2021). "However, KC mice with genetic obesity (Pdx1-Cre;LSL-KrasG12D/+ mice crossed with ob/ob mice) that are leptin deficient also developed PDAC faster, arguing against a causative role of leptin in PDAC." (PMID 34680216, 2021). "In obesity, high leptin levels lead to leptin resistance, which the transporter’s hyperactivation may cause by the high levels of leptin." (PMID 34084149, 2021).
Obesity (continued). "Leptin levels are increased in the circulation of obese individuals, but failed to exert appetite suppression, food lowering, and thermogenic effects in vivo, leading some to propose that leptin resistance also occurs in obesity." (PMID 34260523, 2021). "The critical roles played by leptin in the early development of systems regulating body weight and its subsequent actions within those symptoms has implications for the prevention and treatment of obesity." (PMID 34955895, 2021). "In contrast, the poor response seen in Cluster E may be explained by its highest observed BMI levels and possible systemic inflammation from increased levels of several obesity-associated cytokines (TNF-α, IL-6, and leptin)." (PMID 33705484, 2021). "An interesting model of acquired leptin-resistance is represented by excessive energy intake in larval zebrafish, in which a long-term caloric excess obtained by ad libitum/high-fat diet conditions induces obesity coupled with increased linear growth." (PMID 34684432, 2021). "The leptin/adiponectin ratio correlated with obesity and PWV." (PMID 34680168, 2021). "Besides mouse models with DIO, a recent study showed that KC mice with genetic obesity (Pdx1-Cre;LSL-KrasG12D/+ mice crossed with leptin-deficient [ob/ob] mice) also developed PDAC faster and succumbed to the disease earlier." (PMID 34680216, 2021). "Chronic inflammation, as a result of the increased release of leptin and pro-inflammatory cytokines by adipocytes and related immune cells, likely contributes to the manifestation of elevated ferritin levels in individuals with obesity." (PMID 33920604, 2021). "Plasma leptin level is considered one of the key biomarkers for obesity and metabolic diseases." (PMID 34879063, 2021). "While only 1-5% of the morbidly obese population can be attributed to a mutation related to leptin or its receptor, these models still have use as they recapitulate the leptin resistance and attenuation of leptin signaling that occurs during diet induced obesity." (PMID 34777390, 2021). "In obesity, LEP is increased but cannot bind to its receptors; thus, processes of fatty acid oxidation might be impaired, which can lead to intracellular accumulation of lipid intermediates." (PMID 34151535, 2021). "We tested whether GABA-T knockdown in obesity may have improved leptin sensitivity as a potential mechanism to decrease appetite and cause weight loss." (PMID 34192532, 2021). "Leptin, produced by adipose tissue, is increased in obesity (in serum and plasma)." (PMID 33924402, 2021). "We used the following keywords for the first search topic: (obesity AND adults AND exercise AND anaerobic threshold) AND plasma catecholamine OR epinephrine OR norepinephrine OR lactic acid OR potassium OR growth hormone OR GH OR leptin." (PMID 34047810, 2021). "However, with excess adipose tissue, there are increased leptin levels, which lead to the hypothalamic insensitivity that is characteristic of obesity." (PMID 34659962, 2021). "Among the three studied adipokines, only leptin explained, in part, the relationship between abdominal obesity and arterial stiffness, because the inclusion of leptin in the statistical model attenuated the relationship between obesity and vascular stiffness." (PMID 34202323, 2021). "Consistent with this hypothesis, it was reported that the replacement of Tyr985 with Phe promotes diet-induced leptin resistance and obesity." (PMID 34356668, 2021). "Our results show that in individuals with overweight/obesity, higher circulating levels of adiponectin, but not leptin, resistin, or visfatin, were associated with an increased RA risk." (PMID 34201946, 2021). "Thus, the authors concluded that GDM mediates pre-pregnancy obesity’s effects on placental LEP methylation." (PMID 34502370, 2021).